IL2 (interleukin 2)
Diseases named in the same sentence as IL2 in open-access papers (continued):
Sharing a sentence is not in itself a finding about the gene and the disease.
malaria (continued). "Quantification of levels of pro-inflammatory cytokines, including TNF-α, IFN-γ, IL-1β, IL-2, IL-8, IL-6, IL-12, and GM-CSF in children with malaria in the three transmission areas revealed a pattern of decreasing cytokine levels with increasing transmission intensity (Accra > Navrongo > Kintampo)." (PMID 28399920, 2017). "However, other cytokine responses are important, for example IL-2 is involved in the development of memory responses and antibodies following vaccination against malaria, Hepatitis B and tick-borne encephalitis." (PMID 28892515, 2017). "Moreover, malaria infection inhibits immune responses to the parasite itself, and CD4+ T cells from malaria-infected mice and humans have defects in the ability to produce IL-2 in response to T-cell receptor stimulation." (PMID 27867385, 2016). "In summary, immigrants returning from endemic areas with malaria had higher serum concentrations for some cytokines/chemokines (IL-2, IL-5, IL-8) compared to semi-immune adults with malaria, suggesting that this profile is associated with a partial loss of immunity." (PMID 23967342, 2013). "We examined the associations between the frequencies of IFNγ-IL2+TNF−, IFNγ-IL2+TNF+, and IFNγ-IL2-TNF+ T cells and T cells expressing at least TNF or at least IL2 on stimulation with CSP and subsequent risk of clinical malaria in the 6 months that followed the measurement." (PMID 23300801, 2012). "Moreover, intracellular IL-2 production coincides with increase of Treg cell population in the spleen during P. chabaudi malaria." (PMID 22272258, 2012). "In addition to age, the clinical status of malaria may help explain the inconsistency in IL-2 levels between malaria patients and uninfected individuals." (PMID 41194029, 2025). "Moreover, findings on the role of IL-2 in malaria patients have been inconsistent." (PMID 41194029, 2025). "Incidentally, it is noteworthy in this context that the interplay of CLEC2I:KLRB1F is known to co-stimulate T cell proliferation and Il-2 production, that in turn might contribute to faster development of adaptive immune mechanisms directed against P. chabaudi blood-stage malaria." (PMID 33202767, 2020). "A population of monofunctional CD8+ T cells, positive for IFNγ, but not for IL-2 or TNFα, previously found associated with delay to patency following controlled human malaria infection of malaria-naïve adult volunteers using this vaccine was detected in all three infant groups." (PMID 29213269, 2017). "In addition, significantly higher levels of IL-2 were detected in children (8.2 {8.2; 54.93} pg/mL), travelers (17.03 {8.2; 27.42} pg/mL) and expatriates (15.77 {8.2; 19.7} pg/mL) compared to malaria-exposed adults (8.2 {8.2; 8.2} pg/mL; P = 0.0379, P = 0.0003, P = 0.0144, respectively)." (PMID 23437061, 2013). "Additionally, non-malarial febrile diseases in malaria-endemic areas and genetic predispositions, such as IL-2 gene polymorphisms, could influence IL-2 levels." (PMID 41194029, 2025). "On admission, the concentrations of IL-1β (p = 0.0026), IL-2 (p < 0.0001), IL-6 (p = 0.0009), TNF-α (p > 0.0001), and IFN-γ (p > 0.0001) were significantly upregulated in patients with malaria and typhoid comorbidity, comparing to healthy controls." (PMID 40014608, 2025). "Most of the cytokines that were investigated in malaria and other parasite coinfections were TNF, IFN-γ, IL-2, IL-4, IL-6, and IL-10." (PMID 36716305, 2023). "It was also shown that interleukin-2 (IL-2) levels decreased in mothers with HIV and with coinfection before increasing in mothers with malaria." (PMID 36692923, 2023). "Distinct cytokine profiles in malaria and intestinal parasite coinfections were TNF, IL-2, IL-4, IL-6, and IL-10." (PMID 36716305, 2023). "In the complicated malaria lot, higher levels of IFN-γ and TGF-β and lower levels of IL-2 and IL-12a were reported when compared to the uncomplicated malaria cases." (PMID 34790829, 2021).
malaria (continued). "IFN-γ, IL2, and IFN-γ+IL2 responses to SPZ are likely recognizing hundreds to thousands of malaria antigens." (PMID 34415964, 2021). "As a first step to understanding the contributions of antigen-specific responses, we analyzed IFN-γ, IL2, and IFN-γ+IL2 responses to four lead malaria vaccine antigens expressed by the pre-erythrocytic parasite stages: CSP, AMA1, TRAP and CelTOS." (PMID 34415964, 2021). "In fact, antigen-specific T cells defined by CD40L expression that were also producing TNFα or IL2 induced by RTS,S/AS vaccination were higher in individuals protected from malaria." (PMID 30065162, 2018). "In this study, we revealed that only the non-Vγ9 γδ T cells from people living in malaria-endemic areas proliferated and produced IL-10 in PBMC cultures stimulated with IL-2 and/or Pf Ag for 10 days." (PMID 28769886, 2017). "Intracellular cytokine production (IFN-γ, TNFα, IL2, and IL17A) from PBMC stimulated with pooled malaria and schistosoma antigens was measured in 24 SP Mal and 24 SN Mal children (n = 48)." (PMID 29449839, 2017). "IL-2 expression can also induce NK activation and secretion of IFN-γ, a key effector cytokine involved in malaria protection." (PMID 28878775, 2017). "Recently, a unique subpopulation of malaria-specific CD4+ T cells was revealed to produce IL-27 in response to T-cell receptor stimulation, subsequently inhibiting IL-2 production and clonal expansion of other T cells." (PMID 27867385, 2016). "On the other hand, malaria patients produced lower levels of TNF-α, IL-12p70, and IL-2 than healthy individuals." (PMID 24741587, 2014). "In both malaria and coinfected groups the median levels of TNF-α, IL-2, IL-10, IL1-β, MCP-1, and IL-6 were observed to be mostly significantly increased compared with those intestinal parasites and uninfected groups (P < 0.001 for all comparisons)." (PMID 25309052, 2014). "After evaluating the cytokine profile (IL-2, IL-4, IL-6, IL-10, TNF-α, IFN-γ and IL-17) in the patients’ sera, levels of IL-6, IL-10 and IFN-γ were elevated in malaria patients compared to HV." (PMID 23723981, 2013). "Compared to malaria-exposed adults, children, travelers and expatriates had higher concentrations of IFN-γ (P≤0.0090), IL-2 (P≤0.0379) and IL-8 (P≤0.0233)." (PMID 23437061, 2013). "We find that vaccination of malaria-exposed children with RTS,S/AS01E induces IFNγ-IL2+TNF− and IFNγ-IL2+TNF+ CD4+ T cell responses upon in vitro stimulation of whole blood with CSP peptides." (PMID 23300801, 2012). "While the children in this study had detectable CS-specific IL-2+ CD4+ T cells, these responses were lower than those seen, using a PBMC based assay, in malaria naïve adults vaccinated with RTS,S/AS01 or RTS,S/AS02." (PMID 21494604, 2011). "In this study we investigated the role of commonly accepted factors for Foxp3 induction, TCR stimulation and cytokines such as IL-2, TGFβ and IL-10, in the generation of human CD4+CD25+Foxp3+ T cells by the malaria parasite Plasmodium falciparum." (PMID 19680449, 2009). "This systematic review and meta-analysis found no consistent evidence of altered IL-2 levels in individuals with Plasmodium infection compared to uninfected controls, nor between patients with severe and non-severe malaria." (PMID 41194029, 2025). "One study found that IL-2 levels were not detectable in both severe and uncomplicated malaria cases (< 2 pg/ml)." (PMID 41194029, 2025). "Correlation analysis in this study revealed that IL-2 equally gave a strong negative correlation with IFN-γ in the typho-malaria group (r = −0.577, p < 0.008)." (PMID 40014608, 2025). "Meanwhile, some studies (n = 2, 16.7%) reported increased IL-2 levels in severe malaria patients compared to those with non-severe malaria." (PMID 41194029, 2025). "Six studies provided data for a meta-analysis comparing IL-2 levels between patients with severe malaria (n = 328) and those with non-severe malaria (n = 366)." (PMID 41194029, 2025).
malaria (continued). "For publication years, studies from 2020 to 2024 and 2000–2009 showed negative SMDs, indicating lower IL-2 levels in severe malaria, while studies from 2010 to 2019 showed no alteration in IL-2 levels between the two groups." (PMID 41194029, 2025). "Recently, based on the same scRNA-seq data, we hypothesized and validated roles for IL-2 signalling and the chemokine receptor, CCR5, in balancing Thf/Tfh differentiation in malaria." (PMID 40132035, 2025). "Additionally, there was a positive correlation between perceived stress scores and IL-2 (r = 0.365, p = 0.002), IFN-γ (r = 0.248, p = 0.03), and IL-6 (r = 0.412, p = 0.0001) in the typho-malaria group." (PMID 40014608, 2025). "Increased TNF, IFN-γ, IL-1, IL-2, IL-6, IL-10, TGF-β, CCL2, CCL3, and G-CSF levels and decreased IL-5, IL-12, IL-17, and CCL11 levels were observed in malaria monoinfection compared to intestinal parasite monoinfection." (PMID 36716305, 2023). "Our results showed that rVSV vaccines containing malaria antigens could induce both CD4+ and CD8+ T cells secreting IFN-γ and IL-2." (PMID 36504817, 2022). "Similarly, studies assessing cytokine responses in subjects immunized with vaccines such as hepatitis B, tetanus toxoid or malaria (RTS’S/AS and AMA-1), have shown that TNF and IL-2 are the main cytokines detected following immunization." (PMID 34597297, 2021). "Also, elevated levels of TGF-β, TNF-α, IL-10, and IL-1β were found in cerebral malaria, while IL-2, IFN-γ, IL-5, IL-6, and IL-12 were only increased in mild malaria." (PMID 31878288, 2019). "Human CD4 T cells express P2X7 receptor and secrete IL-2 following eATP stimulation, but it is still unknown whether P2X7 signaling influences the CD4 T cell response in malaria patients." (PMID 28859168, 2017). "In a mouse model of malaria using P. berghei, the parasite ortholog of macrophage migration inhibitory factor (PMIF) induced the upregulation of T-bet and IFN-γ and the downregulation of IL-7R, IL-7, IL-2 and Bcl-2 in T cells specific for the parasite." (PMID 25559491, 2015). "Lymphocyte from control subjects not exposed to malaria showed no significant response of IL-2, TNF, IFN-γ or IL-10 production upon PvMSP1P-19 stimulation compared to the medium control." (PMID 25889175, 2015). "In RTS/S vaccine recipients, malaria-specific CD4+ T cells producing TNFα in the absence of IFNγ or IL-2 have recently been shown to correlate with protection from malaria infection." (PMID 24415936, 2014). "Furthermore, there was a strongly significant synergistic interaction between CSP-specific IFNγ-IL2-TNF+ CD4+ T cells and anti-CSP antibodies in determining protection against clinical malaria (p = 0.002)." (PMID 23300801, 2012). "The concomitant production of IL-2 and expression of high affinity IL-2R by activated CD4+ T cells during acute infection implicates this cytokine as a participant in the immune response to P. chabaudi malaria." (PMID 22272258, 2012). "The mechanisms of Treg induction by the malaria parasite, however, and the potential contribution of the factors (TCR stimulation, IL-2 and TGFβ) remain unknown." (PMID 19680449, 2009). "However, for the malaria group, four distinct correlation patterns were observed; first pattern (CCL4, CCL2, CCL3, IL12 and IL2), second pattern (IL-17A, IL-1β, CCL11, IL4), third pattern (IL5, IL7, IL13), and fourth pattern (IL1RA, CXCL10, TNFα, IL2R, CXCL9, IL6)." (PMID 35811678, 2022). "Importantly, a large percentage of malaria antigen-specific CD4+ and CD8+ T cells produced both TNF-α and IFN-γ (with or without MIP-1β), with the remainder generating individual cytokines including IL-2." (PMID 30673723, 2019). "However, vaccination with RTS,S/AS01E did not significantly enhance IFNγ-IL2-TNF+ CD4+ T cell responses above those induced by natural exposure to malaria alone." (PMID 23300801, 2012).
malaria (continued). "The strong negative correlation between IL-2 and IFN-γ suggests that these two cytokines have opposing effects in the immune response to typho-malaria." (PMID 40014608, 2025). "In the gene expression analysis, elevated levels of TNF-α and IFN-γ with downregulation of IL-2 and upregulation of TGF-β mRNA levels were observed in patients with severe malaria, but not in patients with uncomplicated malaria." (PMID 35954703, 2022). "A correlation matrix revealed a correlation between IL-2 and IL-17F with TNF-α in the OP group, but no other cytokine correlations were detected in the malaria patients and Pf infected children." (PMID 29555909, 2018). "Although P. vivax and P. falciparum malaria patients have similar cytokine profiles during infection, in P. vivax acute phase malaria, APRIL but not BAFF levels correlated positively with IL‐1, IL‐2, IL‐4, IL‐6, and IL‐13 levels." (PMID 29314720, 2018). "However, in many cases such as in studies on malaria, rabies, and influenza, these enhanced secondary responses are at least partly attributable to indirect activation of NK cells by memory T cell-derived IL-2 rather than to true “memory” on the part of NK cells themselves." (PMID 28337195, 2017). "Schistosoma antigen recognition was measured with significant IL-2 and IFN-γ expression observed after PBMC stimulation in the majority of SP children (78% malaria transmission; 82% dry season) but not in SN children." (PMID 22348117, 2012). "We showed for the first time that PBMC from malaria-non-exposed RTS,S-immunized subjects contain both TE/EM and TCM cells that generate strong IL-2 responses following re-stimulation in vitro with CSP peptides." (PMID 21779319, 2011). "Indeed, our findings showed that, in P. vivax acute phase malaria, APRIL but not BAFF levels correlated positively with IL‐1, IL‐2, IL‐4, IL‐6, and IL‐13 levels." (PMID 29314720, 2018). "In a prospective birth cohort study in Kenya, children of malaria-infected women whose CBMC did not produce cytokines (IFN-γ, IL-2, IL-13, and/or IL-5) in response to blood stage malaria antigens were at increased risk of infection and had lower hemoglobin levels during childhood." (PMID 24130857, 2013). "The phenotype of CSP-specific CD4+ T cells that has been associated with vaccine-induced protection against clinical episodes of malaria is TNF-α+, but not IL-2+ or IFN-γ+;56,79 and in part, TNF-α+ CD4+ T cells may also be induced by natural exposure to malaria parasites." (PMID 28934066, 2018). "The results showed that at days 2 and 4, IL-2 was significantly up-regulated in plasma of CXCL-10-/- than in WT, indicating that the absence of CXCL-10 promotes IL-2 expression during murine malaria and that it could play an important role in the pathogenesis of severe malaria." (PMID 21439091, 2011).
ovarian carcinoma (80 papers, 1995 to 2025). A malignant neoplasm originating from the surface ovarian epithelium. "It was also shown that culture of ovarian cancer associated TRegs in presence of IL-2 resulted in their conversion to Th17 cells." (PMID 23272176, 2012). "In the presence of IL-2, human ovarian cancer-associated CD4+ regulatory T cells have also been shown to convert into proinflammatory IL17-producing helper T cells in vitro." (PMID 23272176, 2012). "We have previously reported that ovarian cancer patients with platinum-refractory disease, who were treated with IP IL-2 and responded favorably, had markedly increased eosinophils and serum CXCL11/eotaxin at the completion of treatment." (PMID 40642792, 2025). "Tumor-associated T and NK cells from ovarian carcinoma ascites exhibited defective signaling proteins, including reduced TcR-zeta chain and p56 (lck) expression, along with decreased IFN-γ, IL-2, and IL-4 gene expression." (PMID 41375063, 2025). "Another study combining CIML with IL-2 support has shown benefits for ovarian cancer patients, with ongoing research evaluating adverse events and clinical responses." (PMID 41375063, 2025). "In ovarian cancer, this virus encoding TNF-α and IL-2 can counter immunosuppression and enhance TIL antitumor responses." (PMID 41024300, 2025). "Ex vivo activation of NK cells with cytokines like IL-2, IL-12, IL-15, or IL-18 enhances proliferation, cytokine secretion, and the ability to lyse ovarian cancer cell lines, even those with low MHC-I expression." (PMID 41375063, 2025). "A recent study reported the synthesis of “Mini DCs”, wherein the membranes extracted from the DCs of ovarian cancer patients were coated with IL-2-loaded PLGA NPs." (PMID 40333202, 2025). "Studies suggest endometriosis as a contributing factor in ovarian cancer, with cytokines IL-2, IL-5, IL-6, IL-8, and IL-10 detected in serum, intra-cystic fluid, and peritoneal fluid in endometriomas and ovarian cancer patient samples." (PMID 39596309, 2024). "Tregs in ovarian cancer lesions suppress the immune response to tumor-associated antigens, which is achieved by suppressing the secretion of Interferon gamma (IFN-γ) and interleukin-2 (IL-2) by effector T cells." (PMID 39770446, 2024). "Another study used DC-based vaccine combined with low doses of IL-2 is in phase I/II clinical trial for ovarian cancer patients." (PMID 36631633, 2023). "Our authors have previously reported a phase I/II trial of a therapeutic DC vaccination with IL-2 as a consolidation therapy for ovarian cancer patients." (PMID 36596856, 2023). "In another work, amniotic fluid MSCs were employed to investigate targeted ovarian cancer therapy, which required the usage of Lipofectamine 2000 to transfect MSCs with a plasmid that contained fluorescent IL-2." (PMID 36742134, 2023). "Tregs found in ovarian cancer tumors and ascites suppress an immune response to cancer-associated antigens, which is achieved by the suppression of IFN-γ and IL-2 secretion by effector T cells." (PMID 36428581, 2022). "In this study, our cell coculture experiment confirmed that 5T4 CAR T cells have a specific concentration‐dependent killing effect on 5T4+ ovarian cancer cells in vitro and can secrete Th1 cytokines (IL‐2, IFN‐γ) response upon specific antigen encounter." (PMID 34766126, 2020). "Cytokine-induced killer (CIK) cells (derived again from peripheral blood and stimulated with antiCD3 mAbs, IFN-γ and IL-2) demonstrated enhanced cytotoxic activity compared to LAK cells against ovarian cancer." (PMID 30791364, 2019). "Previously, prolonged survival in a patient with recurrent ovarian cancer successfully treated with intra-peritoneal interleukin-2 was reported." (PMID 31443604, 2019). "Upon exposure to either inflammatory factors including IFNα, IL-15, IL-12 and IL-2, or ovarian cancer cells, NK cells primed by IL-18 can release chemokines CCL3 and CCL4 to attract immature dendritic cells (iDCs)." (PMID 28929459, 2018).